RN7SKP38 (RN7SK pseudogene 38)
Gene: Miscellaneous RNA gene on chromosome 2 (218,500,729 to 218,501,037, reverse strand). Ensembl gene ENSG00000222714.
Homologues: Orthologues: chimpanzee 7SK (86% identical). Paralogues in human: 7SK (76% identical), RN7SKP255 (76% identical), RN7SKP203 (75% identical), RN7SKP9 (75% identical), RN7SKP79 (75% identical), RN7SKP74 (74% identical), RN7SKP78 (74% identical), RN7SKP102 (74% identical), RN7SKP166 (74% identical), RN7SKP173 (74% identical), RN7SKP282 (74% identical), RN7SKP6 (74% identical), and 284 more.